TNFRSF12A (TNF receptor superfamily member 12A)
Diseases named in the same sentence as TNFRSF12A in open-access papers (continued):
Sharing a sentence is not in itself a finding about the gene and the disease.
tumor (continued). "In the miRNA-mRNA negative regulatory networks, miR-204-5p regulated the largest number of target genes, such as TNFRSF12A. miR-146b, miR-204, miR-7-2, and FN1 were associated with tumor stage in PTC, and TNFRSF12A and CLDN1 were related to prognosis." (PMID 30414611, 2018). "In comparison with the control group, except for miR-204-5p, the expression levels of ITGA2, FN1, ICAM1, CDH2, TIMP1, CLDN1, TNFRSF12A, miR-146b, and miR-222 were all up-regulated in the tumor group, consistent with the results of the bioinformatics analyses." (PMID 30414611, 2018). "Notably, CAF-FAP and CAF-C7 both showed upregulated chemokine signaling pathway, but showed high expression of pro-inflammatory genes (CCL2, CXCL12, GDF15, and LIFR) at tumor core and pro-fibrotic genes (TNFRSF12A, TGFBR1, TGFBR2) at FR, respectively." (PMID 39870619, 2025). "Although no study has clearly revealed the direct relationship between TNFRSF12A (TWEAK receptor) and the JAK/STAT pathway in inflammation, it has been demonstrated that TWEAK/Fn14 induces IFNβ and promotes apoptosis in tumor cells via the JAK-STAT pathway, and this process is JAK-dependent." (PMID 40299566, 2025). "Furthermore, scratch and Transwell assays demonstrated a significant decrease in the migratory and invasive abilities of the TNFRSF12A-knockdown tumor cells in contrast to the control group." (PMID 39224598, 2024). "Collectively, these results suggest that PLAU may be an independent biomarker for predicting the outcomes of HNSCC patients and potentially contribute to tumour immunosuppression either in concert with or via TNFRSF12A." (PMID 35327656, 2022). "However, in non-metastasis conditions, the TNFSF12 ligand from eCAFs/myCAFs increased communications with TNFRSF25, while in metastasis conditions, this ligand increased communication with TNFRSF12A in p-EMT tumor cells." (PMID 35742914, 2022). "This suggests that TNFRSF12A might be responsible for the increased migration of drug-resistant tumor cells." (PMID 33937046, 2021). "The signaling pathways activated by TNFRSF12A ultimately lead to tumor cell invasion and migration." (PMID 33937046, 2021). "There are numerous potential approaches to tumor therapy using TNFRSF12A as a target." (PMID 33937046, 2021). "Among 9 CMGs in CMS, TNFRSF12A showed the most notable difference between tumor and normal tissues." (PMID 34434928, 2021). "TNFRSF12A was found to be a tumor promoter via in vitro experiments." (PMID 34434928, 2021). "Importantly, the protein-level verification analysis showed that the upregulation and downregulation of proteins between normal and tumor samples were consistent with the expression of TNFRSF12A." (PMID 33643183, 2021). "Tumor necrosis factor receptor superfamily member (TNFRSF12A) may serve a role in tumor growth and metastasis and has been reported to be elevated in several types of cancer." (PMID 32385351, 2020). "Additionally, miR-146b, miR-204, miR-7-2, and FN1 were associated with the tumor stage of PTC, and TNFRSF12A and CLDN1 were related to the prognosis of PTC." (PMID 30414611, 2018). "Besides, result of qRT-PCR also showed that miR-204-5p expression was significantly decreased while TNFRSF12A expression was significantly increased in tumor compared with control." (PMID 30414611, 2018). "In particular, the genes ADAM9, AXL, and TNFRSF12A may connect directly between mesenchymal tumor cells and stromal cells." (PMID 22570691, 2012). "However, these experimental interventions might present stronger specific effects than the actual physiological processes in the tumor because the experimental process might result in TNFRSF12A expression levels that far exceed those in actual tumors." (PMID 33937046, 2021). "Interestingly, in certain tumor types, TNFRSF12A exhibits a low expression level." (PMID 34917619, 2021).
tumor (continued). "Moreover, in terms of PIK3R3, RNASE7, and TNFRSF12A, similar results have been obtained in other researches, indicating that these genes might be engaged in immune-related pathways and promote tumor progression." (PMID 33193693, 2020). "TMX4, ALPL, PTX3, BHLHE40, TNFRSF12A and CST3 demonstrated significant overexpression in LUSC tumour tissues, whereas CLDN1, VKORC1 and ADD3 exhibited significant underexpression in the HPA database." (PMID 38520221, 2024). "All but one (ARG1) of the proteins with significantly lower expression at baseline in the p16+ tumour group also showed lower expression at 12 months—that is, PTN, TNFRSF12A, CD28, and CD70." (PMID 36835246, 2023). "The analysis discovered four subtypes of CAFs, one p-EMT tumor cell and cycling tumor cell population, as well as the roles of TNFSF12–TNFRSF25/TNFRSF12A interactions in CAFs and p-EMT tumor cells during tumor metastasis at the single-cell level." (PMID 35742914, 2022). "A new type of human TWEAK receptor antibody (TweakR, Fn14, TNFRSF12A, and CD266) PDL192 was found to directly inhibit tumor cell growth and antibody-dependent cytotoxicity in a variety of mouse xenograft models, showing strong antitumor effects active." (PMID 35707713, 2022). "While AASEs of tumor-related genes, such as ARMC3, TPM4, and TNFRSF12A had higher inclusion levels in G3." (PMID 35989380, 2022). "Simultaneously, downregulation of TNFRSF12A also dampened the migration ability of HNSCC cell lines, consolidating its role as a tumor promoter in HNSCC carcinogenesis." (PMID 34434928, 2021). "Notably, TMX4, ALPL, PTX3, BHLHE40, TNFRSF12A and CST3 demonstrated significant overexpression in LUSC tumour tissues, whereas CLDN1, VKORC1 and ADD3 exhibited significant underexpression." (PMID 38520221, 2024). "TNFRSF12A, when bound to its ligand TNF-like weak inducer of apoptosis (TWEAK), can activate multiple signaling pathways, thereby affecting the tumor microenvironment and promoting tumor cell survival and migration." (PMID 39119480, 2024). "In addition, the expression levels of ORC1, TNFRSF12A, TRAF1 and TIAM1 were also positively correlated with tumor grade to a certain extent." (PMID 37005685, 2023). "For discrimination of the normal and tumour sampling zones, we were able to derive an effective gene-based classifying model for molecular abnormality based on a panel of eight genes (MMP1, MMP12, MYO1B, TNFRSF12A, WDR66, LAMC2, SLC16A1 and PLAU)." (PMID 35327656, 2022). "Tumor samples from high-risk group A showed a higher mean overall IHC score for Anti-MSX1, Anti-CD271, Anti-ERRFI1, Anti-PTPRF, Anti-TNFRSF21, Anti-TNFRSF12a, and Anti-IGFBP2, but without significance." (PMID 30641895, 2019). "Beyond tumor growth, we also detected several DEGs enriched in metastasis, including vinculin (VCL) and Tumor necrosis factor (TNF) receptor superfamily member 12A (TNFRSF12A)." (PMID 30301189, 2018). "In other words, CD27, EDA, TNF, TNFRSF12A, TNFRSF13C, and TNFRSF9 expression may also affect the immunotherapy effect on tumours by regulating the expression of immune checkpoint molecules in the tumour microenvironment." (PMID 35392242, 2022). "Therefore, we hypothesised that CD27, EDA, TNF, TNFRSF12A, TNFRSF13C, and TNFRSF9 may affect tumour prognosis mainly by regulating the TGF-β signaling pathway." (PMID 35392242, 2022). "Furthermore, six tumor progression genes (GNAI2, ODC1, APP, TNFRSF12A, BASP1, and LARP6) and nine migration and metastasis‐related genes (MSN, FLOT1, LAMB3, MYL9, ITGB1, FTH1, TPM4, and PMEPA1), which could explain the invasive characteristics of SCC, were identified." (PMID 40776410, 2025).
cancer (91 papers, 2010 to 2025). A tumor composed of atypical neoplastic, often pleomorphic cells that invade other tissues. "used the expression levels of α-SMA and TNFRSF12A to differentiate between cancer associated fibroblast (CAF) subpopulations." (PMID 40391219, 2025). "The TNFRSF12A gene, part of the tumor necrosis factor receptor superfamily, plays a key role in molecular pathways linked to various cancers." (PMID 40595248, 2025). "A single-cell transcriptomics analysis (TISCH2 database) revealed that TNFRSF12A is highly expressed in cancer-associated fibroblasts (CAFs) and positively correlated with CAF markers (FAP: ρ = 0.304; PDPN: ρ = 0.364)." (PMID 41300305, 2025). "Immune infiltration profiling (TIMER/TISCH2) revealed selective enrichment of TNFRSF12A in cancer-associated fibroblasts (CAFs)." (PMID 41300305, 2025). "The relationship between the MMP-9 and TNFRSF12A needs to be proven through experimentation; however, we speculated that TNFRSF12A associated with high MMP-9 expression might accelerate cancer progression through increased angiogenesis." (PMID 30142200, 2018). "Numerous evidences have manifested that the dysregulation of TNFRSF12A plays an important part in the triggering and development of malignant tumors." (PMID 40391219, 2025). "We first acquired sample data from the public database to reveal the expression pattern of TNFRSF12A in pan-cancer and assess its correlation with patient prognosis and clinical features in STAD." (PMID 40391219, 2025). "TNFRSF12A (Fn14) is a receptor for the TWEAK ligand, frequently overexpressed in many cancers, associated with cell survival, migration, and metastasis." (PMID 41440381, 2025). "TNFRSF12A is also found to be overexpressed in various carcinomas, which usually indicates a poor prognosis." (PMID 40391219, 2025). "Of note, TWEAK and its receptor TNFRSF12a (TNF receptor superfamily member 12a, also known as Fn14 or TWEAK receptor) are associated with various pathophysiological conditions including inflammation and cancer, but also MN." (PMID 38897568, 2024). "Recent research has highlighted the significant impact of TNFRSF12A on the development, advancement, and metastasis of different types of cancer in humans." (PMID 39224598, 2024). "Inhibition of TNFRSF12A has been found to attenuate cancer-related cachexia and extend patient survival." (PMID 38660262, 2024). "We found that TNFRSF12A expression was transcriptionally induced during glutamine deprivation in cancer cell lines." (PMID 37761958, 2023). "TNFRSF12A is a member of the TNF superfamily of receptors that has been reported to be elevated in different cancers." (PMID 37291533, 2023). "Among the non-NFκB/TNF hallmark genes that received votes across all 16 cancer types, four genes (SRGN, CCN2, TNFRSF12A, and ZFP36L1) with an average vote exceeding 900 have been reported as regulated by TNF and NFκB." (PMID 37475016, 2023). "TNF receptor superfamily member TNFRSF12A (Fn14) also interacts with this pathway, is upregulated in many cancers, and has recently been shown to promote EMT in human bronchial epithelium." (PMID 27876705, 2016). "Tumor necrosis factor receptor superfamily, member 12a (Tnfrsf12a), also known as fn14 or TWEAK-R have been implicated in a variety of pathological processes including chronic inflammation and cancers." (PMID 22206623, 2011). "TNFRSF12A/TWEAK has been found to be prognostic in several cancer types." (PMID 35805022, 2022). "The results revealed that angiogenesis, glycolysis, and EMT were the biological process most correlated with CD44 expression, while the TNFα signaling via NFκB, angiogenesis, IL6_JAK_STAT3 pathway, and EMT were correlated with TNFRSF12A in cancer cells across CRC, LC, and SCC." (PMID 34676217, 2021). "In cancer, TNFRSF12A can promote angiogenesis and endothelial cell proliferation." (PMID 30857150, 2019).
cancer (continued). "In addition, it could also be a critical therapeutic target, and preclinical studies have shown that the use of inhibitors in cancer with high TNFRSF12A expression has certain effects." (PMID 34917619, 2021). "Therefore, TNFRSF12A has different expression patterns in different cancers and could be a remarkable feature for distinguishing different cancer cell lines." (PMID 34917619, 2021). "Conversely, the six downregulated genes (SERPINE1, TNFRSF12A, PHLDA1, RNASEK, PPIA, and G0S2) are involved in diverse cancer-related pathways." (PMID 40340807, 2025). "The qRT-PCR results of the clinical samples also showed that the mRNA expression of CD27, TNF, TNFRSF12A, TNFRSF13C, and TNFRSF9 is upregulated in cancer tissues, except EDA whose mRNA expression is downregulated in cancer tissues." (PMID 35392242, 2022). "TNFRSF12A is also highly expressed in human HCC, and in vivo experiments have revealed that TNFRS12A knockdown can inhibit cancer cell proliferation and migration." (PMID 34917619, 2021). "On the other hand, a new set of potential biomarkers (NCKAP1, TNFRSF12A, LAMB2, FKBP9, PFN2, TOM1L1) and expression rules for the identification of different cancers at the transcriptome level were discovered." (PMID 34917619, 2021). "Both TNFRSF12A/TWEAK pair and CD38, along with its interaction partner CD31 are involved in multiple cancers, including NSCLC, where they contribute to escape from PD-1/PD-L1 blockade and cytotoxic therapy." (PMID 32537452, 2020). "As expected, many apoptosis-related genes, involving ARHGEF2, TNFRSF12A, and SFRP2, were hypermethylated in CMT, and some oncogenes in human cancers, HRAS, FAM83H, and RET, were found as hypomethylated." (PMID 31569550, 2019). "We focused on the genes TNFRSF12A, CD44 and NFKB2 in more detail given their role in the multiple cellular pathways and cancer and the high scoring of the corresponding switching events." (PMID 30857150, 2019). "Both PAR2 and PAR1 activation resulted in up-regulated expression of several genes (CD44, FOSL1, TNFRSF12A, RAB3A, COPEB, CORO1C, THBS1, SDC4) known to be important in cancer." (PMID 21072196, 2010). "Normal B and cancer 1 clusters shared inflammatory markers CCL2, TNFRSF12A, and IL1R1, pathways including TNFα, IL, and Myc signaling, and activity of inflammation, hypoxia, and lipid metabolism–associated transcription factors NFATC2, ARNT, PPARA, and PPARGC1A." (PMID 40215177, 2025). "Data were derived from The Cancer Gene Atlas (TCGA), Gene Expression Omnibus (GEO), and Gene Expression Profiling Interactive Analysis (GEPIA) to analyze the expression pattern of TNFRSF12A in pan-cancer and STAD, as well as its correlation with clinical features." (PMID 40391219, 2025). "This dual role of TNFRSF12A in AD and GBM supports the hypothesis of an overlap relationship between cancer and NDDs, offering new avenues for targeted therapies." (PMID 40595248, 2025). "We show that the upregulation of Tnfrsf12a is independent of the other major metabolic stressors known to affect cancer metabolism such as glucose and serum deprivation." (PMID 37761958, 2023). "Indeed, we highlighted three pan-cancer NFκB/TNF hallmark genes (EGR1, JUNB, and ZNF36) and identified four candidates (SRGN, CCN2, TNFRSF12A, and ZFP36L1) that are highly potentially involved in NFκB/TNF pathways in various cancers." (PMID 37475016, 2023). "TNFRSF12A is the smallest member of the TNF superfamily of receptors; it contains a short cytoplasmic demise domain and has been reported to be elevated in different cancers." (PMID 35646656, 2022). "For instance, TNFRSF12A could result in cancer, chronic autoimmune diseases, and acute ischemic stroke via the TWEAK-TNFRSF12A axis." (PMID 34434928, 2021). "For example, TNFSF12-TNFRSF12A and SPP1-CD44 were shown in LC, CRC, and SCC, indicating that myeloid cells might express and secrete TNFSF12 and SPP1, signaling to their receptors TNFRSF12A and CD44 on cancer cells, respectively." (PMID 34676217, 2021).
cancer (continued). "In our study, Tnfrsf12a's expression is 2.5 fold changes higher in FA2 group than FA3, which may be explained that the degree of colon mucosal damage in FA2 was much worse and was prone to develop to cancers compared to FA3." (PMID 22206623, 2011).
central nervous system diseases (2 papers, 2020 to 2025). "As gene-targeted therapies and ligand-modulating strategies advance, the clinical translation of TNFRSF12A may enable precision interventions that address inflammatory, proliferative, and degenerative states across central nervous system disorders." (PMID 40595248, 2025).
inflammation (1 paper, 2025). Aberrant reaction of the microcirculation characterized by movement of fluid and leukocytes from the blood into extravascular tissues. "Consistent with liver inflammation, the serum levels of pro-inflammatory proteins, including CCL2, CXCL9, IL-17a, IL-17f, and TNF receptor superfamily member 12a, were increased in HF-HC-fed mice." (PMID 41362710, 2025).
respiratory diseases (1 paper, 2022). "Interestingly, TNFRSF12A has been reported many times in previous studies to engage in oxidative stress, and evidence shows that TNFRSF12A plays an important role in respiratory diseases." (PMID 36234635, 2022).
TNFRSF12A also shares sentences with these, for which no sentence is quoted: ischemic stroke (11 papers); kidney disease (11); multiple sclerosis (10); lupus nephritis (9); cardiovascular disease (8); pancreatic cancer (8); liver fibrosis (7); infection (6); muscle atrophy (6); nephritis (6); Alzheimer disease (5); colorectal cancer (5); non-small cell lung carcinoma (5); Sepsis (5); brain diseases (4); breast tumors (4); depression (4); neurological diseases (4); skin inflammatory diseases (4); chronic kidney disease (3); cutaneous lupus erythematosus (3); dementia (3); endometrial cancer (3); heart disease (3); injury (3); lung carcinoma (3); lymph node metastasis (3); Meniere disease (3); myocardial ischemia (3); myopathy (3).
A further 127 diseases each share a sentence with TNFRSF12A in 3 papers or fewer.